ACSL3 (acyl-CoA synthetase long chain family member 3)
Description:
Acyl-CoA synthetases (ACSL) activates long-chain fatty acids for both synthesis of cellular lipids, and degradation via beta-oxidation. Required for the incorporation of fatty acids into phosphatidylcholine, the major phospholipid located on the surface of VLDL (very low density lipoproteins). Has mainly an anabolic role in energy metabolism. Mediates hepatic lipogenesis. Preferentially uses myristate, laurate, arachidonate and eicosapentaenoate as substrates. Both isoforms exhibit the same level of activity (By similarity).
Synonyms: LACS 3; ACS3; FACL3; LACS3; PRO2194
Tractability: Antibody: UniProt predicts a signal peptide or a membrane-spanning region; its Gene Ontology location is reachable by antibodies, with medium confidence. PROTAC: ubiquitination databases record sites on it; its protein half-life has been measured.
Target class: Enzyme; Ligase
Gene: Protein-coding gene on chromosome 2 (222,860,942 to 222,944,639, forward strand). Ensembl gene ENSG00000123983.
Subcellular location: Mitochondrion outer membrane; Peroxisome membrane; Microsome membrane; Endoplasmic reticulum membrane
Subcellular location (Human Protein Atlas): Nucleoli; Nucleoli rim; Lipid droplets
Pathways (Reactome):
Metabolism: Intracellular metabolism of fatty acids regulates insulin secretion; Synthesis of very long-chain fatty acyl-CoAs
Gene Ontology:
Molecular function: long-chain fatty acid-CoA ligase activity; protein binding; protein domain specific binding; protein kinase binding; arachidonate-CoA ligase activity; fatty acid-CoA ligase activity; medium-chain fatty acid-CoA ligase activity; palmitoyl-CoA ligase activity
Biological process: long-chain fatty acid import into cell; long-chain fatty acid metabolic process; positive regulation of Golgi to plasma membrane protein transport; positive regulation of phosphatidylcholine biosynthetic process; positive regulation of secretion; very-low-density lipoprotein particle assembly; fatty acid metabolic process; long-chain fatty-acyl-CoA biosynthetic process; long-chain fatty-acyl-CoA metabolic process; neuron differentiation
Cellular component: endoplasmic reticulum; Golgi apparatus; lipid droplet; membrane; perinuclear region of cytoplasm; endoplasmic reticulum membrane; mitochondrial outer membrane; plasma membrane; peroxisomal membrane
Genetic constraint (gnomAD): Loss-of-function variants: 32 observed, 71 expected, observed/expected ratio (o/e) 0.45, 90% interval 0.34 to 0.61. The upper end of that interval is the gene's LOEUF score, 0.61, which puts it in group 2 of 6, group 1 being the genes least tolerant of losing a copy. Missense variants: 595 observed, 787.58 expected, observed/expected ratio (o/e) 0.76, 90% interval 0.7 to 0.81. Synonymous variants: 271 observed, 271.33 expected, observed/expected ratio (o/e) 1, 90% interval 0.9 to 1.1.
Homologues: Orthologues: chimpanzee ACSL3 (100% identical), macaque ACSL3 (99% identical), rabbit ACSL3 (95% identical), guinea pig ACSL3 (95% identical), pig ACSL3 (94% identical), mouse Acsl3 (93% identical), rat Acsl3 (92% identical), dog ACSL3 (92% identical), tropical clawed frog acsl3 (74% identical), zebrafish acsl3b (73% identical), Caenorhabditis elegans acs-15 (25% identical), Caenorhabditis elegans acs-18 (25% identical), and 22 more. Paralogues in human: ACSL4 (62% identical), ACSL5 (31% identical), ACSL1 (31% identical), ACSL6 (29% identical), ACSBG1 (21% identical), ACSBG2 (20% identical), SLC27A4 (16% identical), SLC27A3 (16% identical), SLC27A1 (16% identical), SLC27A2 (16% identical), SLC27A5 (16% identical), SLC27A6 (15% identical).
Diseases named in the same sentence as ACSL3 in open-access papers:
ACSL3 is named in the same sentence as 82 diseases in open-access papers, as found by Europe PMC text mining. Sharing a sentence is not in itself a finding about the gene and the disease. The quoted sentences say what the papers report.
lung carcinoma (29 papers, 2009 to 2025). "The ACSL family has been implicated in lung cancer, with elevated expression of ACSL3 and ACSL4 observed in this disease." (PMID 41288931, 2025). "A lung cancer study showed that KAS mutations drive ACSL3 expression, thereby promoting fatty acid absorption, retention, accumulation, and beta-oxidation in cancer cells, and identified ACSL3 as a potential metabolic therapeutic target." (PMID 37993451, 2023). "ACSL3 overexpression increased cell proliferation, migration, and invasion altering the metabolic properties of lung cancer cells and was associated with worse clinical outcomes in patients with high-grade NSCLC." (PMID 34249899, 2021). "An in silico study also suggested that high ACSL1 expression was associated with worse survival in lung cancer patients, and ACSL3 overexpression was associated with worse survival in patients with melanoma." (PMID 33030783, 2020). "An in silico study also suggested that high ACSL1 expression was associated with worse outcome in lung cancer patients, and ACSL3 overexpression was associated with worse survival in patients with melanoma." (PMID 33194695, 2020). "KRAS mutations in lung cancer also increase the expression of Acyl-coenzyme A synthetase long chain family member 3 (ACSL3) to reprogram lipid metabolism, promote Monounsaturated fatty acids-phospholipids (MUFA-PL) biosynthesis and ferroptosis resistance, and facilitate lung cancer progression." (PMID 38273826, 2023). "Interestingly, a high level of acyl-coA synthetase family member 3 (ACSL3) was observed in human lung cancer, and the enzyme was found to play an essential role in the tumorigenesis of lung cancers bearing KRAS G13D mutation." (PMID 33466836, 2021). "In lung adenocarcinoma, ACSL3 is upregulated in tumor tissues, and its silencing induces lipid peroxidation and ferroptosis in lung cancer cells, suggesting potential therapeutic benefits." (PMID 41288931, 2025). "The 8 FRGs (ACSL3, FADS2, GLS2, HSF1, PANX1, PHKG2, VDAC2, and CDKN1A) that we selected to be associated with the diagnosis and prognosis of lung cancer have been shown to play important roles in cancer and tumor immunity." (PMID 38743344, 2024). "Mutant KRAS promotes FAO through acyl-coenzyme A (CoA) synthetase long-chain family member 3 (ACSL3) in lung cancer cells in an ACSL3-dependent manner." (PMID 38841622, 2024). "The expression of some proteins of the ferroptosis pathway (SLC7A11 and ACSL3) was also decreased after insufficient RFA of lung cancer cells." (PMID 37948404, 2023). "High expression level of ACSL3 increased the sensitivity of NSCLC lung cancer cells to simvastatin treatment." (PMID 37248280, 2023). "ACSL3 has similar expression profiles in other cancer types, such as pancreatic cancer, breast cancer, lung cancer, and prostate cancer." (PMID 36338658, 2022). "Human lung cancers were demonstrated to also express high levels of ACSL3, one of the enzymes responsible for the conversion of FAs into acyl-CoA esters, the substrates for β-oxidation and lipid synthesis." (PMID 35159223, 2022). "In lung cancer, ACSL3 plays an essential role in mediating the activation and channeling of extracellularly derived FAs into mitochondria for fatty acid oxidation and prostaglandin synthesis." (PMID 34998392, 2022). "The results of our transactivation assays show that TGFβ1 exposure up-regulates the transcriptional activity of ACSL3. mTORC1 signaling pathway has been reported to mediate the up-regulation of ACSL3 expression in mutant KRAS lung cancer cells." (PMID 35414781, 2022). "This study uncovers the ACSL3-LPIAT1 axis as a requirement for the sustained prostaglandin synthesis in lung cancer with potential therapeutic value." (PMID 32034305, 2020). "Overexpression of the enzyme ACSL3 is an unfavorable prognostic marker in non‐small cell lung cancer (NSCLC)." (PMID 33030783, 2020).
lung carcinoma (continued). "On the other hand, bioinformatic analyses and tumor tissue microarray (TMA) staining showed that ACSL3 is up-regulated in lung cancer compared to the healthy lung tissue." (PMID 31344914, 2019). "The increased ACSL3 in U87 human glioblastoma cell drives the tumorigenesis, whereas ACSL3 knockdown reduces lung cancer cell growth." (PMID 27171439, 2016). "We then employed a lung cancer cell line (H1299) to demonstrate that the demethylation of ACSL3 5′-CGI by 5-aza-dC treatment induced enhancement of gene expression in H1299." (PMID 19221603, 2009). "Similar to the expression pattern of ACSL5, ACSL3 was lost in most of the lung cancer cell lines, and, based on the expression of ACSL3 in primary lung tumor, we consider that ACSL3 might be involved in lung ADC differentiation." (PMID 38539505, 2024). "Interestingly, ACSL3 has also been proposed as a pharmacological target for mutant KRAS lung cancer, pancreatic cancer, clear cell renal cell carcinoma, and colorectal carcinoma." (PMID 38879607, 2024). "ACSL3 is an unfavorable prognostic marker in liver cancer and lung cancer." (PMID 38539505, 2024). "ACSL3 is highly expressed in human lung cancer specimens and it can promote cancer initiation." (PMID 36728187, 2023). "Lung cancer tissues showed moderate‐to‐strong ACSL3 cytoplasmic immunoreactivity." (PMID 33030783, 2020). "Moreover, the overexpression of ACSL3 increased cell proliferation, migration, and invasion altering metabolic properties of lung cancer cells." (PMID 33030783, 2020). "Therefore, it is plausible that LPIAT1 and ACSL3 can sustain lung cancer proliferation by also serving other pathways." (PMID 32034305, 2020). "Besides, tumor tissue microarray (TMA) staining showed that ACSL3 is upregulated in lung cancer compared to the healthy lung tissue." (PMID 33030783, 2020). "Here, we found that the overexpression of a fatty acid‐related ACSL3 enzyme could be considered as an unfavorable prognostic marker in non‐small cell lung cancer (NSCLC)." (PMID 33030783, 2020). "ACSL3 is found to be upregulated in fibrosarcomas, ER-negative, prostate cancer, melanoma, hepatocellular carcinomas and lung cancer, suggesting that targeting ACSL3 in this context may be clinically relevant for many cancers." (PMID 31344914, 2019). "Previous study indicates that ACSL3 is overexpressed in lung cancer." (PMID 27171439, 2016). "Indeed, KRAS-driven lung cancer has a greater resistance to ferroptosis owing to a reprogrammed lipid metabolism by a higher level of acyl-coenzyme A synthetase long-chain family member 3 (ACSL3) expression." (PMID 36864513, 2023). "Moreover, ACSL3 has been shown to be essential for mutant KRAS lung cancer tumorigenesis." (PMID 34790661, 2021). "Nevertheless, our data indicate that ACSL3 significantly enhances prostaglandin synthesis in tumors compared with healthy lung, suggesting that this may fulfill the increased requirement for prostaglandin synthesis of lung cancer." (PMID 32034305, 2020). "However, a few analyses gave the inconsistent trend in one cancer, including the outcome of ACSL3 in lung cancer of GSE13213 and GSE31210 datasets, the expression of ACSL4 in Buchholz and Badea pancreatic cancer datasets, and the expression of ACSL5 in Hou and Okayama lung cancer datasets." (PMID 27171439, 2016). "Beyond ACSL3 and ACSL4, ACSL5 has been reported to influence lung cancer cell behavior by modulating the effects of lysophosphatidylcholine through the remodeling of transcriptional regulators." (PMID 41288931, 2025). "Compared to the NHBE cells, the mRNA expression of ACSL1, ACSL3, and ACSL6 was downregulated in all the lung cancer cell lines." (PMID 38539505, 2024). "We found that, compared to normal human bronchial epithelial (NHBE) cells, ACSL1, ACSL4, and ACSL6 were highly expressed, while ACSL3 and ACSL5 were lost in the majority of lung cancer cell lines." (PMID 38539505, 2024).
lung carcinoma (continued). "We previously provided evidence that ACSL3 mediates the activation and retention of extracellularly derived FAs in KRAS mutant lung cancer cells." (PMID 34998392, 2022). "Here, we found that, in mutant KRAS and in a subset of wild-type KRAS lung cancer cells, high prostaglandin levels are sustained by LPIAT1 activity and depend on the ACSL3-activated AA substrate availability." (PMID 32034305, 2020). "Thapsigargin-induced ER stress results in the downregulation of ACSL3, ACSL4 and solute carrier family 27 member 2 (SLC27A2) in lung cancer." (PMID 31344914, 2019). "In addition, we confirmed the increase in mRNA and protein levels of ACSL3 and ACSL4 in brain and lung cancer cells, which was similar with the iTRAQ data, illustrating that ferroptotic markers are upregulated by NCI677397." (PMID 38140768, 2024). "In human lung cancer cells, we found that the proteins of ACSL1, ACSL4, and ACSL6 were highly expressed in most of the lung cancer cell lines observed, while the proteins of ACSL3 and ACSL5 were lost in the majority of the lung cancer cell lines, compared to the NHBE cells." (PMID 38539505, 2024). "A study on lung cancer has indicated that the absence of ACSL3 leads to intracellular ATP depletion, which aligns with our previous observations in cells following BRD4 inhibition." (PMID 37993451, 2023). "ACSL3 silencing induced cell death in vitro by depleting cellular ATP and impaired tumor growth in vivo, suggesting the involvement of this enzyme in mutant KRAS lung cancer growth." (PMID 35159223, 2022). "In summary, we identified that the four ferroptosis suppressor genes, ACSL3, CISD1, FANCD2, and SLC3A2, could increase the cancer stemness, indicating that the lower the ferroptosis level in lung cancer cells, the higher the tumor heterogeneity." (PMID 34434214, 2021). "Thus, a downregulation of ACSL3 observed in MBTPS2 mutant cells may alter cellular metabolism, energy production and cell survival, similar to that observed in lung cancer cells." (PMID 34093655, 2021). "Furthermore, the up-regulation of ACSL3, which has recently demonstrated to be essential for tumorigenesis in KRAS-driven lung cancer, may also be involved in activating mitochondrial respiration from fatty acids." (PMID 33806075, 2021).
melanoma (23 papers, 2016 to 2025). A malignant, usually aggressive tumor composed of atypical, neoplastic melanocytes. "Downstream from FASN, saturated and unsaturated fatty acids are activated into fatty acyl-CoA by the acyl-CoA synthetase long-chain (ACSL) family members, and notably, ACSL3 expression has been associated with poor prognosis in melanoma patients." (PMID 34830962, 2021). "Of note, the expression of ACSL3 has been also associated to a worse prognosis in melanoma." (PMID 33121001, 2020). "High level of ACSL3 was associated with poor outcome in melanoma patients." (PMID 33091721, 2020). "Thus, it is clear that ACSL3 inhibits ferroptosis by increasing membrane stability through its involvement in the remodelling of PL-MUFAs, and that high expression of ACSL3 in human melanoma is associated with poorer prognosis." (PMID 37736551, 2023). "Meanwhile, ACSL3, which belongs to the same family as ACSL4, is also associated with the poor prognosis of melanoma." (PMID 41170386, 2025). "One study indicates that the abundant oleic acid in lymphocytes protects melanoma cells from ferroptosis in an ACSL3-dependent manner." (PMID 41170386, 2025). "The authors noted that ACSL3 was expressed by most human and mouse melanomas, including all of the efficient metastasizers whereas some of the inefficient metastasizers expressed little ACSL3." (PMID 39706856, 2024). "Oleic acid protects melanoma cells from ferroptosis in an ACSL3-dependent manner, thereby facilitating melanoma metastasis." (PMID 37868994, 2023). "Oleic acid can also inhibit melanocyte ferroptosis and enhance metastasis in an ACSL3-dependent manner, and melanoma patients with high expression of ACSL3 have a lower survival rate." (PMID 37894410, 2023). "Although OA protects melanoma cells against ferroptosis, ACSL3-deleted melanoma cells undergo ferroptosis even in the presence of OA, supporting a critical role for ACSL3 in MUFA-mediated ferroptosis suppression." (PMID 37612411, 2023). "Intriguingly, ACSL3 has also been linked with melanoma metastasis in a preclinical PDX model, whereby oleic acid, an abundant fatty acid present in lymph, protected melanoma cells from ferroptosis in an ACSL3-dependent manner." (PMID 34830962, 2021). "The previous studies indicate that ACSL3 overexpression was associated with worse clinical outcomes in patients with NSCLC and melanoma; in contrast, high ACSL3 expression predicted a better prognosis in ovarian cancer." (PMID 34819946, 2021). "Authors identified that ACSL3 is responsible for incorporation of oleic acid in the membrane of melanoma cells in lymphnode and thus protects metastatic cells from ferroptotic cell death." (PMID 33091721, 2020). "High ACSL3 expression predicted a better prognosis in ovarian cancer; in contrast, high ACSL3 predicted a worse prognosis in melanoma." (PMID 27171439, 2016). "We identified the co-expression profiles for ACSL3 with a strong cluster of 27 genes across a panel of 185 ovarian carcinoma and 10 normal ovary tissues and 229 genes across a panel of 45 melanoma and 25 normal samples." (PMID 27171439, 2016). "The better prognosis in ovarian cancer patient and the worse prognosis in melanoma patient with higher ACSL3 expression were in accordance with the result from Oncomine." (PMID 27171439, 2016). "This ACSL3-dependent anti-ferroptotic mechanism may be active in vivo and contribute to metastasis: ACSL3 activity promotes the survival of metastatic melanoma cells that transit through the lymph fluid where they are exposed to a MUFA-rich environment." (PMID 38908072, 2024). "Oleic acid can protect melanoma cells from ferroptosis in an ACSL3‐dependent manner." (PMID 36728187, 2023). "Among the 5 mammalian ACSL families ACSL3 has been detected in several types of cancer and high expression correlates with worse prognosis in patients with melanoma and triple negative breast cancer and might be involved in prostate carcinogenesis." (PMID 36624406, 2023).
melanoma (continued). "Moreover, a recent study reported that oleic acid, an abundant FA in lymph, protected melanoma cells from ferroptosis in an ACSL3-dependent manner and increased their capacity to form metastasis." (PMID 33121001, 2020). "Because ACSL3 regulates lipid droplet biogenesis and maintenance, it would be interesting to investigate whether the lipid droplet increase and therapy resistance in melanoma patients is mediated by ACSL3." (PMID 31344914, 2019). "ACSL3 is upregulated in melanoma, and its levels correlate with a worse patient prognosis, but the molecular mechanism regarding its role is unknown." (PMID 31344914, 2019). "Our analysis revealed that ACSL3 was down-regulated in ovarian cancer and up-regulated in melanoma." (PMID 27171439, 2016). "The oncogenic role of ACSL3 in melanoma is consistent with a previous study." (PMID 27171439, 2016). "The metastases included in this tissue array were gastrointestinal in origin so the performance of ACSL3 and ACSL4 combined biomarker will need to be assessed in relation to other common metastatic tumours such as those arising from lung, breast and melanoma." (PMID 32286604, 2020). "The up-regulation of CPT1, ACSL3, SLC27A5, and associated PC content was primarily detected in SOX6 + C1/C2 melanoma cells, suggesting that fatty acid transport, rather than fatty acid oxidation, constitutes the primary mechanism in AM metastasis." (PMID 40866912, 2025). "ACSL3 was coexpressed with SNUPN, TRIP13, and SEMA5A in melanoma." (PMID 27171439, 2016).